CCL2 (C-C motif chemokine ligand 2)
Diseases named in the same sentence as CCL2 in open-access papers (continued):
Sharing a sentence is not in itself a finding about the gene and the disease.
breast cancer (continued). "Specifically, tumor-secreted CCL2 stimulates neutrophils to accumulate in the lung prior to the arrival of metastatic cells and inhibits metastatic seeding by generating H2O2 in breast cancer mice." (PMID 30792719, 2019). "CCL2 and CCR2 expression are chronically overexpressed in multiple cancer types including: glioblastoma, prostate, colon and breast cancer." (PMID 31208996, 2019). "Blockade of the CCL2/CCR2 axis led to reduction of monocyte infiltration in multiple TIME and inhibits breast cancer cell metastatic seeding." (PMID 31611871, 2019). "We found only three small molecules, which concentration differs significantly in both luminal A and luminal B subtypes of breast cancer: IL-13, MCP-1 (CCL2), and MCP-3 (CCL7)." (PMID 31861498, 2019). "We then measured CCL2 mRNA expression and its release from various viable and apoptotic breast cancer cell lines along with HMEC, which corroborated a positive correlation of miR-375 levels and CCL2 expression." (PMID 30850595, 2019). "The correct reference is “Soria, G.; Ben-Baruch, A., The inflammatory chemokines CCL2 and CCL5 in breast cancer." (PMID 31146450, 2019). "Taken together, we determined that IL-6, CCL2, MMP9, MMP2, and CHOP expression are all inversely correlated with IGF-1R expression in human breast cancer." (PMID 30458886, 2018). "Surprisingly, CCL2 has also been reported to negatively regulate ICAM1 expression and breast cancer metastasis." (PMID 30585203, 2018). "It is well-known that IL-6, CCL2, and MMP9 expression are increased in TNBC compared to ER+/PR+ breast cancer." (PMID 30458886, 2018). "Activation of the CCL2/CCR2 axis increased secretion of CCL3 by MAMs, which in turn facilitated metastatic seeding of breast cancer cells in the lung." (PMID 29594035, 2018). "Previous analysis of the human patient gene expression datasets revealed IL-6, CCL2, and MMP9 expression are upregulated in TNBC compared to ER+/PR+ breast cancer." (PMID 30458886, 2018). "In the MMTV-PyMT mammary tumor model, a decrease in the number of TAMs in the tumor site was observed in Ccr2-null background animals, suggesting the importance of CCR2/CCL2 signaling in the recruitment of TAMs to tumor sites." (PMID 29686671, 2018). "In mice, interference with the CCL2/CCR2 axis significantly reduced the growth of hepatocellular and renal cell carcinomas, and abrogated breast cancer metastasis." (PMID 29594035, 2018). "Exposing MSCs to conditioned media derived from metastatic breast cancer cells resulted in increased levels of chemokines, such as CXCL1, 3, 5, 6, 8, CCL2 and CCL7." (PMID 29760166, 2018). "In this study, we are trying to draw attention to a CCL2 chemokine and its receptor CCR2, the levels of which are statistically significantly different in breast cancer patients compared to control groups." (PMID 30151375, 2018). "Further analysis of the METABRIC dataset revealed an increase in IL-6, CCL2, and MMP-9 expression in patients with low IGF-1R, consistent with our mouse tumor model and data in human breast cancer cell lines." (PMID 30458886, 2018). "A macrophage-tropic chemokine, CCL2, was produced by breast cancer cells in lungs, to recruit circulating monocytes expressing CCR2, a specific receptor for CCL2, to the tumor sites." (PMID 30597969, 2018). "The aim of this study was to investigate plasma levels and applicability of CCL2, CCR2, and tumor marker CA 15-3 in breast cancer (BC) patients and in relation to the control groups: patients with benign breast tumor and healthy subjects." (PMID 30151375, 2018). "The CCL2/CCR2 pair actively participates in tumor progression and metastasis: high serum levels of this chemokine correlated with poor prognosis in breast carcinoma patients." (PMID 30591657, 2018). "For example high CCL2 expression suggested improvement in RFS for basal (p = 0.047), HER2+ (p < 0.001) and luminal B (p = 0.047) breast cancers." (PMID 28143493, 2017).
breast cancer (continued). "However, examination of the relationship between high CCL2 expressing basal-like, HER2+ and luminal B breast cancer patients revealed that higher CCL2 expressing tumors in these subgroups have a significantly higher probability of surviving longer than those expressing low CCL2." (PMID 28143493, 2017). "Our findings supported by human data show that breast cancer patients with high-levels of IL-1β, CXCL1, CCL2, S100A8, VEGF, and IL-8 would show worse clinical outcomes." (PMID 29262555, 2017). "Some chemokines, including CCL2, CCL18, CCL9, were reported to recruit the ly6c(+) monocyte into the tumor microenvironment in murine breast cancer and colon cancers." (PMID 28694739, 2017). "Previous studies in breast cancer cells have demonstrated that FXYD5 knockdown decreases, while FXYD5 overexpression increases, both the NF-κB-responsive promoter activity and CCL2 production in cancer cells." (PMID 28620381, 2017). "In this study, we show that breast cancer cells increase production and secretion of IL6, IL8, CSF2 and CCL2 cytokines after withdrawal of chemotherapeutic drugs (paclitaxel, 5-fluorouracil or doxorubicin)." (PMID 28703802, 2017). "In summary, the obtained findings suggest that there exists a TNFα evoked release of CCL2 and other LSP recruiting cytokines from human breast cancer cells, which can be attenuated by apigenin." (PMID 28441391, 2017). "We observed statistically significant higher mRNA expression levels (lower delta Ct values) for CCL2, IL1B and OPG in the stage I breast cancer samples relative to normal samples." (PMID 28143606, 2017). "These chemokines are also known to regulate the expression of the pro-inflammatory cytokines MCP-1 (monocyte chemotactic protein-1; CCL2), IL-8 (CXCL8), and RANTES (CCL5) in breast cancer." (PMID 27515302, 2016). "The chemokines that participate in the migration of MDSCs in breast cancer include CXCL5, CCL1 and CCL2 (also known as monocyte chemotactic protein-1 (MCP-1)) and CCL5." (PMID 27542274, 2016). "By contrast, CCRL2 overexpression was reported to inhibit CCL2-induced phosphorylation of p38 MAPK leading to decreased chemotaxis and invasion of human breast cancer cells." (PMID 27907906, 2016). "We have demonstrated that targeted disruption of Ccl2 and pharmacologic inhibition of CCR2 both delay the growth of mammary tumors and prolong survival of mice carrying the MMTV-neu transgene." (PMID 27820834, 2016). "Taken together, our data suggest a tumor-promoting role for CCL2 acting through CCR2 on the tumor microenvironment and support the targeting of this chemokine/receptor pair in breast cancer." (PMID 27820834, 2016). "It has been reported that targeting CCL2/CCR2 signaling axis remarkably reduced the motility and survival of breast cancer cells." (PMID 27409666, 2016). "Several chemokines that are known to recruit myeloid cells (CCL2, CCL9, CXCL2), including monocytes and neutrophils, were expressed by metastatic breast cancer cells." (PMID 25882816, 2015). "On the other hand, CCL2 signaling is known to be enhanced in breast cancer, a condition present in the case AD3 of our cohort, which displays particularly high pGlu-CCL2 levels." (PMID 25666182, 2015). "In a different study, CCL2 induced the expression of the intercellular adhesion molecule ICAM-1 on human lymphatic endothelial cells and thereby facilitated the attachment of breast cancer cells to lymphatic endothelial cells." (PMID 25950608, 2015). "Metastatic breast cancer cells expressed chemokines that can direct the recruitment of T lymphocytes (CXCL9, CCL2 or CX3CL1)." (PMID 25882816, 2015). "Another study demonstrated that chemokine CCL2 and its receptor CCR2 are needed for human Vδ1T cell infiltration into various tumors including lung, prostate, liver, or breast cancers." (PMID 24565056, 2014). "Some studies have shown that CCL2 and CCL5 expressions are higher in breast cancer tissue than in corresponding normal tissue." (PMID 24591761, 2014).
breast cancer (continued). "Specifically, fibroblast-secreted amphiregulin promoted breast cancer cell survival, whereas the chemokine CCL7 stimulated tumor cell proliferation while CCL2 promoted innate immune cell infiltration and angiogenesis." (PMID 24068959, 2013). "MCP-1/CCL2 expression in human tumors correlates with monocyte/macrophage infiltration, as well as advanced tumor stages and metastatic relapse in breast cancer patients." (PMID 24314323, 2013). "To determine if this indeed the case, we have initiated this study by determining the expression patterns of CCL2, CCL5, TNFα and IL-1β in biopsy sections of healthy individuals and in breast cancer patients at different progression stages of disease." (PMID 21486440, 2011). "The inflammatory chemokines CCL2 (MCP-1) & CCL5 (RANTES) and the inflammatory cytokines TNFα & IL-1β were shown to contribute to breast cancer development and metastasis." (PMID 21486440, 2011). "Further, biochemical studies of breast cancer cell lines from various subtypes could be helpful in clarifying the mechanisms through which CCR2 and MET overexpression regulates CCL2 and HGF signaling." (PMID 40736024, 2025). "Consistent with our results, other reports have shown that treatment with a CCL2-neutralizing antibody or genetic knockout of CCL2 suppresses lung metastasis, but not primary tumor growth, in in vivo models involving mouse and human breast cancer cells." (PMID 40343498, 2025). "In summary, these findings on CCL2/CCR2 and HGF/MET signaling in early-stage breast cancer could be used to tailor treatments for patients with DCIS." (PMID 40736024, 2025). "CCL2/CCR2 and HGF/MET signaling pathways are upregulated in breast cancers." (PMID 40736024, 2025). "Understanding the specific mechanisms that regulate CCL2 and HGF expression are regulated in breast cancer may enable us to predict when CCR2 and MET signaling may be altered during breast cancer progression." (PMID 40736024, 2025). "Given the cooperative effects between CCL2 and HGF on breast cancer cells, we hypothesized that targeting CCR2 or MET alone would inhibit DCIS progression more effectively than inhibiting CCR2 or MET alone." (PMID 40736024, 2025). "Notably, levels of CCL2 and CCL5 are significantly elevated in the blood of breast cancer patients, particularly those with ER-positive tumors, and positively correlate with TAM infiltration." (PMID 40909271, 2025). "CCL2/CCR2 and HGF/MET cooperate to enhance breast cancer progression and metabolic reprogramming." (PMID 40736024, 2025). "In addition, CCL2 also synergetic with HGF/MET pathway to promote the progression and metabolic reprogramming of breast cancer, and the combination of CCR2 knockout and MET inhibitor meritinib can more effectively inhibit tumor growth and stromal response." (PMID 41341593, 2025). "In breast cancer, EZH2 and DNMT1 act synergistically to regulate CCL2 expression." (PMID 41341593, 2025). "Also, a feedback loop between TAM-released CCL2 and activated PI3K/Akt/mTOR pathway in tumor cells is a possible mechanism for endocrine resistance in breast cancer patients." (PMID 39003350, 2024). "This overexpression increases monocyte recruitment and promotes the migration of HER2 + breast cancer cells through the CCL2/CCR2/MAPK pathway, underscoring the significant impact of TAM-derived MMP-11 on the progression and metastatic potential of breast cancer." (PMID 38713256, 2024). "Promising results have been obtained using CCL2 siRNA, CCR2 siRNA, CCL2-neutralizing antibodies, CCL2 inhibitors, or CCR2 antagonists to treat tumours like breast cancer, glioma, and hepatocellular cancer in laboratory animals that received cancer cell implantation." (PMID 38339377, 2024). "Bioinformatics analysis of in silico publicly available TNBC data identified BCL3 and BCL2 as well as the following anti-tumour immune response biomarkers as significantly altered in TNBC compared to other breast cancer subtypes: GZMA, PRF1, CXCL1, CCL2, CCL4, and CCL5." (PMID 38022682, 2023).
breast cancer (continued). "We hypothesized that the CCL2 paracrine in the TME establishes a network consisting of tumor cells, MSCs, and TAMs; consistently, it was suggested that breast cancer-derived CCL2 is involved in the homing effect of human MSCs." (PMID 36672395, 2023). "In addition to having angiogenic activity, CCL2, CXCL2, and MMP-9 can also act as chemokines to recruit tumor cells, myeloid-derived cells, and macrophages, providing conditions for breast cancer metastasis while promoting further deterioration of the tumor." (PMID 38003338, 2023). "Indeed, the mRNA expression levels of CXCL2, TGFB1, CCL2, and IL1B were markedly increased in the breast cancer cell lines after treatment with Doxo and Abe." (PMID 37993606, 2023). "In addition, the knockdown of CCL2 and inhibition of its receptor resulted in delayed tumor growth in the MMTV-HER2 breast cancer model." (PMID 36674955, 2023). "Using an in vitro generated HER2-overexpressed EGFR+ cell line model, this study found that several cytokines, such as CCL2, were increased by HER2 overexpression, leading to a pro-tumoral microenvironment through the CCL2-mediated trafficking of TAMs in breast cancer." (PMID 36674955, 2023). "Among these different CAF subtypes, iCAFs are reported to have a particular effect on chemoresistance in breast cancer patients, probably due to their high secretion of cytokines involved in therapy resistance, such as CXCL1–3, CCL2, CSF3, CXCL10, IL1β and LIF." (PMID 36710348, 2023). "CCL2, a dominant monocyte chemoattractant protein to recruit macrophages through binding to CCR2, was found to be a key mediator for osteoclastogenesis in bone metastasis of breast cancer and prostate cancer." (PMID 35715847, 2022). "Notably, other group has published the regulation of CCL2 expression by PARP1/pADPr in breast cancer cells and demonstrated the importance of PARP1 localization in promoter for CCL2 effective transcription." (PMID 35585513, 2022). "In a breast cancer model, CCL2 recruited CCR2-expressing inflammatory monocytes to the lung to facilitate pulmonary metastasis, while we have shown a similar role for CCL2 in liver metastasis of colorectal cancer." (PMID 36241867, 2022). "Thus, inhibition of TAMs recruitment by targeting CCL2 or CCR2 has successfully reduced tumor burden in melanoma, breast cancer, and so on." (PMID 35844580, 2022). "In addition, incubation of MDA-MB-231 and HCC1937 breast cancer cells with TGF-β1 (10 ng/mL, for 24 h) led to a 1.5–twofold increase in the level of CCL2 promoter activity in the luciferase reporter system." (PMID 34239022, 2021). "Additionally, in vitro studies have demonstrated that CCL2/CCR2 mediated p42/44MAPK and SMAD3 pathways in breast cancer cells are important in growth, survival, migration and invasion." (PMID 33888841, 2021). "Trastuzumab treatment down-regulates CCL2 production in animal experiments, and increases PD-1 expression, total immune cell and follicular helper T-cell infiltration clinically in HER2-enriched breast cancer." (PMID 34439387, 2021). "Reciprocally, endocrine‐resistant breast cancer cells activate the mTORC1‐FOXK1 pathway of macrophages by altering amino acid metabolism in the microenvironment, which enhances M2 macrophage polarization and CCL2 secretion by macrophages." (PMID 35250965, 2021). "It is evident that CCL-2 and CCL-5 could act as prognostic local biomarkers and are involved in breast cancer progression, but further research is needed since many of the included studies have small sample sizes." (PMID 34944905, 2021). "CCL2 production has been reported to be more inducible in HER2+/ER− breast carcinoma cells compared with HER2+/ER+ cells under EGF/HRG stimulation, and enhanced NF-κB transcription levels were detected in HER2+/ER− breast carcinoma cells." (PMID 34386431, 2021). "Further, in breast cancer patients, expression data revealed a correlation between Notch activation, IL-1ß/CCL2 expression, and macrophage infiltration." (PMID 33981303, 2021).